BTN3A1 (butyrophilin subfamily 3 member A1)
Diseases named in the same sentence as BTN3A1 in open-access papers (continued):
Sharing a sentence is not in itself a finding about the gene and the disease.
infection (9 papers, 2014 to 2025). The state of being infected such as from the introduction of a foreign agent such as serum, vaccine, antigenic substance or organism. "Vγ9Vδ2+ T cells, as the main subset of γδ T cells in human peripheral blood, are involved in immune responses in infections, tumors, and inflammation, and their function is associated with BTN3A1." (PMID 40959207, 2025). "The T cell costimulators ICOSLG (inducible T cell costimulator ligand) and PD-L2 were downregulated during infection, as was butyrophilin subfamily 3 member A1 (BTN3A1), recently shown to present phosphoantigens to Vγ9Vδ2+ T cells." (PMID 24906157, 2014). "This BTN3A1-independent activation may correspond with cytokines induced in these cells following Lm-infection, as has previously been described." (PMID 34381163, 2021). "Conformational changes of BTN3A1 might represent a key step in the detection of infection or tumorigenesis by γδ T cells." (PMID 32435249, 2020). "Recent reports support that conformational modifications of BTN3A1 might represent a key step in the detection of infection or tumorigenesis by Vγ9Vδ2 T cells." (PMID 29731756, 2018). "Infection of Jurkat T cells with the BTN3A1+/+ adenovirus (MOI = 200, Day 6) and injection of BTN3A1+/+ adenovirus (109 PFU, Day 5) in WT mice showed the optimal expression of BTN3A1, respectively." (PMID 40959207, 2025). "Infection with RHΔompdcΔup induced high IFNγ levels, and these were significantly diminished by a BTN3A1‐blocking antibody but not by an IgG1 isotype control." (PMID 41452934, 2025). "Studies have shown that through binding to P-Ags presented by BTN3A1 and BTN2A1 on infected or malignant cells, γδ T cells could be activated, proliferate rapidly, and induce anti-infection or antitumor responses through IFN-γ production." (PMID 33101298, 2020). "Studies have shown that through the binding to P-Ags presented by BTN3A1 and BTN2A1 on infected or malignant cells, γδ T cells could be activated, proliferate rapidly, and release cytokines to induce anti-infection or antitumor responses." (PMID 33101298, 2020). "The fact that bacterial extracts can activate Vγ9Vδ2 T cells in a HMBPP and BTN3A1-dependent manner may not accurately model in vivo infection, where cellular entry is critical." (PMID 34381163, 2021). "Surprisingly, overexpression of BTN3A1 and BTN3A3 was found to restrict Mallard‐GFP rather than PR8‐GFP or maCal04‐GFP infection, implying that BTN3A3 specifically restricts avian IAVs." (PMID 38045831, 2023).
mental illness (2 papers, 2024 to 2026). "BTN3A1 plays a crucial role in antigen presentation and is highly expressed in the cerebral cortex.This suggests a potential close association between BTN3A1 and psychiatric disorders." (PMID 38637810, 2024). "However, research on the relationship between BTN3A1 and mental illness is still limited and requires further exploration." (PMID 38637810, 2024).
BTN3A1 also shares sentences with these, for which no sentence is quoted: bladder cancer (2 papers); celiac disease (2); depression (2); esophageal squamous cell carcinoma (2); head and neck squamous cell carcinoma (2); pancreatic ductal adenocarcinoma (2); renal cell carcinoma (2); AIDS (1); aortic aneurysm (1); benign ovarian tumors (1); cholangiocarcinoma (1); esophageal carcinoma (1); gastrointestinal stromal tumor (1); glioblastoma (1); lung adenocarcinoma (1); lung squamous cell carcinoma (1); lupus nephritis (1); myocardial infarction (1); non-small cell lung carcinoma (1); osteosarcoma (1); pancreatic adenocarcinoma (1); pancreatic cancer (1); prostate adenocarcinoma (1); psoriasis (1); pulmonary TB (1); rectum adenocarcinoma (1); respiratory diseases (1); sarcoma (1); uterine corpus endometrial carcinoma (1); vasculitis (1).